HDAC2 (histone deacetylase 2)
Description:
Histone deacetylase that catalyzes the deacetylation of lysine residues on the N-terminal part of the core histones (H2A, H2B, H3 and H4). Histone deacetylation gives a tag for epigenetic repression and plays an important role in transcriptional regulation, cell cycle progression and developmental events (By similarity). Histone deacetylases act via the formation of large multiprotein complexes (By similarity). Forms transcriptional repressor complexes by associating with MAD, SIN3, YY1 and N-COR. Component of a RCOR/GFI/KDM1A/HDAC complex that suppresses, via histone deacetylase (HDAC) recruitment, a number of genes implicated in multilineage blood cell development (By similarity). Acts as a component of the histone deacetylase NuRD complex which participates in the remodeling of chromatin. Component of the SIN3B complex that represses transcription and counteracts the histone acetyltransferase activity of EP300 through the recognition H3K27ac marks by PHF12 and the activity of the histone deacetylase HDAC2. Also deacetylates non-histone targets: deacetylates TSHZ3, thereby regulating its transcriptional repressor activity. May be involved in the transcriptional repression of circadian target genes, such as PER1, mediated by CRY1 through histone deacetylation (By similarity). Involved in MTA1-mediated transcriptional corepression of TFF1 and CDKN1A. In addition to protein deacetylase activity, also acts as a protein-lysine deacylase by recognizing other acyl groups: catalyzes removal of (2E)-butenoyl (crotonyl), lactoyl (lactyl) and 2-hydroxyisobutanoyl (2-hydroxyisobutyryl) acyl groups from lysine residues, leading to protein decrotonylation, delactylation and de-2-hydroxyisobutyrylation, respectively.
Synonyms: HD2; RPD3; YAF1; KDAC2
Tractability: Small molecule: an approved drug acts on it; a structure with a bound ligand is known; a high-quality ligand is known; it has a binding pocket of medium quality; it belongs to a druggable protein family. PROTAC: it is named in the literature on targeted protein degradation; UniProt records ubiquitination sites on it; ubiquitination databases record sites on it; its protein half-life has been measured; a small molecule that binds it is known. Other modalities: an approved drug acts on it.
Target class: Eraser; HDAC class I; Epigenetic regulator; Histone deacetylase
Chemical probes: FK228 (high quality), HINOKITIOL, JPS016, PD080688, PD081051, PD081107, PD081295, PD081975, PD082650, PD082670, PD082947, PD083384, PD083802, PD084637, PD085132, pandacostat, santacruzamate A
Gene: Protein-coding gene on chromosome 6 (113,933,028 to 114,011,308, reverse strand). Ensembl gene ENSG00000196591.
Subcellular location: Nucleus; Cytoplasm
Subcellular location (Human Protein Atlas): Nucleoplasm
Pathways (Reactome):
Gene expression (Transcription): ERCC6 (CSB) and EHMT2 (G9a) positively regulate rRNA expression; FOXO-mediated transcription of oxidative stress, metabolic and neuronal genes; NoRC negatively regulates rRNA expression; Notch-HLH transcription pathway; RNA Polymerase I Transcription Initiation; Regulation of endogenous retroelements by KRAB-ZFP proteins; Regulation of endogenous retroelements by Piwi-interacting RNAs (piRNAs)
Signal Transduction: NOTCH1 Intracellular Domain Regulates Transcription; Regulation of PTEN gene transcription; STAT3 nuclear events downstream of ALK signaling; p75NTR negatively regulates cell cycle via SC1
Chromatin organization: HDACs deacetylate histones; Interaction of NuRD complexes with transcription factors; NuRD complex assembly
Developmental Biology: Differentiation of naive CD4+ T cells to T helper 2 cells (Th2 cells); EGR2 and SOX10-mediated initiation of Schwann cell myelination; Transcriptional regulation of brown and beige adipocyte differentiation by EBF2
Disease: Constitutive Signaling by NOTCH1 HD+PEST Domain Mutants; Constitutive Signaling by NOTCH1 PEST Domain Mutants; Potential therapeutics for SARS
Cell-Cell communication: Negative Regulation of CDH1 Gene Transcription
Hemostasis: Factors involved in megakaryocyte development and platelet production
Metabolism of proteins: SUMOylation of chromatin organization proteins
Gene Ontology:
Molecular function: enzyme binding; histone binding; histone deacetylase activity; histone deacetylase activity, hydrolytic mechanism; histone deacetylase binding; histone decrotonylase activity; NF-kappaB binding; nucleosomal DNA binding; protein binding; protein de-2-hydroxyisobutyrylase activity; protein decrotonylase activity; protein lysine deacetylase activity; protein lysine delactylase activity; RNA binding; RNA polymerase II-specific DNA-binding transcription factor binding; transcription coregulator binding; chromatin binding; hydrolase activity, acting on carbon-nitrogen (but not peptide) bonds, in linear amides
Biological process: chromatin remodeling; heterochromatin formation; negative regulation of transcription by RNA polymerase II; positive regulation of cell population proliferation; positive regulation of intracellular estrogen receptor signaling pathway; positive regulation of proteolysis; positive regulation of transcription by RNA polymerase II; progesterone receptor signaling pathway; circadian regulation of gene expression; dendrite development; embryonic digit morphogenesis; epidermal cell differentiation; eyelid development in camera-type eye; fungiform papilla formation; hair follicle placode formation; negative regulation of apoptotic process; negative regulation of cell migration; negative regulation of DNA-templated transcription; negative regulation of neuron projection development; negative regulation of stem cell population maintenance; negative regulation of transforming growth factor beta receptor signaling pathway; odontogenesis of dentin-containing tooth; positive regulation of DNA-templated transcription; positive regulation of stem cell population maintenance; regulation of cell fate specification; and 2 more
Cellular component: chromatin; chromosome, telomeric region; cytoplasm; ESC/E(Z) complex; histone deacetylase complex; nucleoplasm; nucleus; NuRD complex; protein-containing complex; Sin3-type complex; transcription repressor complex
Genetic constraint (gnomAD): Loss-of-function variants: 1 observed, 12.92 expected, observed/expected ratio (o/e) 0.0774, 90% interval 0.027 to 0.37. The upper end of that interval is the gene's LOEUF score, 0.37, which puts it in group 1 of 6, group 1 being the genes least tolerant of losing a copy. Missense variants: 62 observed, 116.46 expected, observed/expected ratio (o/e) 0.53, 90% interval 0.43 to 0.66. Synonymous variants: 43 observed, 38.67 expected, observed/expected ratio (o/e) 1.11, 90% interval 0.87 to 1.43.
Homologues: Orthologues: chimpanzee HDAC2 (100% identical), macaque HDAC2 (99% identical), mouse Hdac2 (99% identical), pig HDAC2 (99% identical), dog HDAC2 (99% identical), guinea pig HDAC2 (99% identical), tropical clawed frog hdac2 (98% identical), rat Hdac2 (94% identical), rabbit HDAC2 (91% identical), Drosophila melanogaster HDAC1 (77% identical), Caenorhabditis elegans F43G6.4 (9% identical), Caenorhabditis elegans hda-5 (6% identical), and 1 more. Paralogues in human: HDAC1 (85% identical), HDAC3 (52% identical), HDAC8 (32% identical), HDAC5 (25% identical), HDAC4 (25% identical), HDAC9 (24% identical), HDAC6 (21% identical), HDAC7 (21% identical), HDAC11 (15% identical), HDAC10 (10% identical).
Diseases named in the same sentence as HDAC2 in open-access papers:
HDAC2 is named in the same sentence as 334 diseases in open-access papers, as found by Europe PMC text mining. Sharing a sentence is not in itself a finding about the gene and the disease. The quoted sentences say what the papers report.
breast cancer (125 papers, 2008 to 2025). A primary or metastatic malignant neoplasm involving the breast. "High levels of HDAC2 were closely associated with the overexpression of human epidermal growth factor receptor 2 and nodal metastasis in breast cancer." (PMID 36968022, 2023). "Increased HDAC2 has been also associated with advanced stage and poor tumor differentiation in gastrointestinal and breast carcinomas." (PMID 36901692, 2023). "For instance, ADGRG6 promotes breast cancer growth upon progesterone stimulation, serves as a mutation marker for bladder cancer recurrence and immunotherapy monitoring, and drives colorectal cancer proliferation via HDAC2 and GLI2 signaling." (PMID 41614755, 2025). "Also, HDAC2 overexpression was associated with more aggressive stage III breast cancers, which significantly correlated with a worse prognosis." (PMID 39063083, 2024). "However, the survival analysis from the online website GEPIA2 revealed an association of high HDAC-2 expression with poor prognosis in breast cancer patients." (PMID 38201636, 2024). "HDAC2, a member of the histone deacetylase family, is located in the nucleus, and its overexpression has been associated with lymph node invasion, higher grade, and poor prognosis in breast cancer." (PMID 37483962, 2023). "Moreover, the survival analysis from GEPIA2 showed that high expression of HDAC2 was associated with poor prognosis of breast cancer patients." (PMID 34365463, 2021). "Further, LMO4 has been shown to associate with HDAC2 (in breast cancer cell lines,) and with CREB." (PMID 22509321, 2012). "Mocetinostat, an inhibitor of HDAC1-3 and HDAC11, induced the expression of tumor suppressor Fyn-related kinase in basal-like breast cancer and showed antitumor effects in those overexpressing HDAC2." (PMID 40165290, 2025). "HDAC2, a histone deacetylase, reportedly promoted cell cycle progression of breast cancer cell lines, since CRISPR/Cas9‐mediated knockout induced reduction of the cells in S and G2/M phases." (PMID 40022573, 2025). "Ginsenoside Rh4 effectively inhibits PD-L1 expression by regulating histone deacetylase 2 (HDAC2)-mediated JAK/STAT signaling pathways in breast cancer cells, while demonstrating high binding affinity with HDAC2 through molecular docking analysis." (PMID 41155644, 2025). "Recent research has explored the connection between HER2 activation and HDAC2 activity, especially in breast cancer therapies." (PMID 41224124, 2025). "To date, Crocus sativus L-derived crocetin β-D-glucosyl ester has been demonstrated—via molecular docking analysis—to exhibit high affinity for HDAC2 and to inhibit breast cancer cell proliferation in vitro." (PMID 40806702, 2025). "In the analysis of the groups with mammary carcinomas, both groups G3 and G4 showed a significant difference between subgroups concerning the positive association of HDAC1 and HDAC2 (p < 0.05)." (PMID 40590021, 2025). "High-level expression of HDAC2 promotes cancer progression through various signal pathways, including breast cancer, non-small cell lung cancer, liver cancer." (PMID 38087046, 2024). "Of note, a correlation analysis between PDK1 and HDAC levels in breast cancer samples from the Cancer Genome Atlas (TCGA) dataset highlighted that high HDAC-2 expression had a poor OS probability." (PMID 38201636, 2024). "Serglycin was found to upregulate YAP through integrin α5/FAK/CREB signaling, resulting in increased histone deacetylase 2 (HDAC2) expression, which modulates stemness and chemoresistance in breast cancer cells." (PMID 39334952, 2024). "As for the expression of the HDAC2 gene, evidence has also reported that HDAC2 is one of the most commonly amplified genes in aggressive basal-like breast cancer." (PMID 37764768, 2023). "Studies have shown that OLE can reduce progression, invasion, and proliferation of breast cancer cells by suppressing the activity of both HDAC2 and HDAC3." (PMID 37764768, 2023).
breast cancer (continued). "Evidence has indicated that HDAC2 is overexpressed in breast cancer cells compared to normal breast tissue." (PMID 37764768, 2023). "Significant difference in HDAC2 expression was displayed between breast cancer tissue and normal breast tissue (p < 0.001, Log2FC, 0.122)." (PMID 37764768, 2023). "And the up-regulation of HDAC2 in breast cancer cells and tissues can also regulate the malignant biological behavior of breast cancer cells." (PMID 37553641, 2023). "We applied it to measurements from breast cancer cell lines and patient biopsies and were able to identify strong remodeling of HDAC2 epigenetic complexes in more aggressive forms of cancer." (PMID 37749212, 2023). "This suggests that the combined action of GE and SFN can influence gene expression in breast cancer cells by modulating HDAC2 activity, thereby affecting immune response." (PMID 37764768, 2023). "miR-155 decreased the expression of erythroblastic oncogene B by targeting HDAC2 in breast cancer cells." (PMID 36968022, 2023). "Based on the findings of our study and previous research, MTA2 and HDAC2 show promise as potential targets for breast cancer treatment." (PMID 37483962, 2023). "The downregulation of HDAC2 and overexpression of miR-646 suppressed breast cancer cell proliferation." (PMID 36968022, 2023). "Mocetinostat, an HDAC inhibitor, showed anti-tumor effects in HDAC2-overexpressing basal-like breast cancer lines." (PMID 36968022, 2023). "For instance, evidence indicates that depleting HDAC2 can sensitize breast cancer cells to apoptosis induced by epirubicin." (PMID 37764768, 2023). "HDACs, such as HDAC2, 4, and 5, have been shown to play a positive role in enhancing tumor progression and drug resistance in HR-positive breast cancer, which is related to their functions in regulating cell proliferation, differentiation, and autophagy." (PMID 36831644, 2023). "DNMT1 recruited EZH2 and the HDAC2 complex to the promoter sequences of miR-148a and decreased miR-148a expression, which led to doxorubicin resistance in breast cancer cells." (PMID 36968022, 2023). "Rh4 can inhibit the expression of PD-L1 by regulating HDAC2-mediated JAK/STAT in breast cancer cells." (PMID 37764768, 2023). "HDAC2 was found to be critical in increasing the motility of MCF-7 breast cancer cells via the induction of metastatic markers such as MMP2 and N-cadherin." (PMID 36831644, 2023). "High expression of HDAC2 and HDAC8 has been demonstrated to be associated with resistance of breast cancer cells to radiation." (PMID 35193602, 2022). "Recent studies have shown that HDAC2 was essential for increasing breast cancer cell motility through the induction of the breast cancer metastasis markers MMP2 and N-cadherin." (PMID 35743249, 2022). "In breast cancer tissues, HDAC2 and EZH2 protein expression levels also were inversely correlated with levels of miR-148a expression." (PMID 35892859, 2022). "In this study, we elucidate that these epigenetic alterations play a vital role in regulating PDK1 and identify the new regulation axis of EZH2/HDAC2/miR-148a/PDK1 in breast cancer progression and therapeutic resistance." (PMID 35892859, 2022). "Many studies reported that HDAC1 is overexpressed in prostate, colon adenocarcinoma gastric, and breast carcinomas, whereas HDAC2 is overexpressed in colorectal, cervical, and gastric cancers." (PMID 35458763, 2022). "Overexpression of HDAC1, HDAC2, and HDAC3 is linked to low survival in patients with gastric and ovarian cancers, while HDAC6 was highly expressed in breast cancer specimens." (PMID 35458763, 2022). "Curcumin has been reported to inhibit HDACs such as HDAC1 and HDAC2 in breast cancer cell lines, MCF-7 and MDA-MBA-231." (PMID 33498667, 2021). "Consistently, high HDAC2 expression is correlated with the poor prognosis of breast cancer patients." (PMID 34365463, 2021).
breast cancer (continued). "These outcomes suggest that dysregulations of HDAC2, HDAC4, and HDAC5 can collaborate with the development of tamoxifen resistance in ER+ breast cancer cells associated with miR-10b and miR-125a-5p deregulation." (PMID 34359587, 2021). "Meanwhile, we also used the online tool GEPIA2 to analyze the HDAC2 and PD-L1 expression in breast cancer and normal breast tissues." (PMID 34365463, 2021). "Next, we studied the effect of HDAC2 knockout on the malignant behaviors of breast cancer cells by carrying out CCK-8, colony formation assay, wound healing, Transwell migration and cell cycle analysis." (PMID 34365463, 2021). "Next, western blotting and RT-PCR were carried out to test HDAC2 and PD-L1 expression in various breast cancer cells, including 3 TNBC cells (MDA-MB-231, BT-549, and 4T-1) and 2 non-TNBC cells (SKBR3, T47D)." (PMID 34365463, 2021). "The HDAC1 and HDAC2 expression levels were constitutively very high in these breast cancer cell lines, comparing to the normal breast epithelial cells MCF-12F." (PMID 33498667, 2021). "HDAC2 is a poor prognostic factor in patients receiving anthracycline therapy and is positively correlated with breast cancer metastasis, progression, increased Ki-67, multidrug resistance protein, and negatively correlated with overall survival of patients." (PMID 33062007, 2020). "SRGN induced or maintained breast cancer stemness and chemoresistance depending on the level of HDAC2." (PMID 32292495, 2020). "For example, wild-type BRCA1 binds to the promoter of miR-155 in breast cancer cells, where it recruits histone deacetylase 2 (HDAC2) to promote chromatin condensation and gene repression." (PMID 30323900, 2018). "Recently, nimbolide was shown to promote H3K27 acetylation by inhibiting HDAC2, eventually inducing autophagy-driven apoptosis of breast cancer cells." (PMID 30352996, 2018). "For example, HDAC1 and HDAC2 are highly expressed in breast cancer and promote tumor progresses, and LSD1 is lowly expressed in breast cancer and inhibits tumor progress." (PMID 30310855, 2018). "Overexpression of HDAC2 protein was detected in human cancers, including gastric, prostate, and breast cancers." (PMID 30071870, 2018). "HDAC2 is another important gene related to breast cancer that is inclined to strongly express in aggressive breast cancer tumor subgroups." (PMID 29179495, 2017). "In this study, we found that the MCF7-derived, ER+, estrogen-independent, tamoxifen-resistant MCF7-TamC3 breast cancer cells exhibit increased expression of HDAC2 and HDAC5 as compare to the estrogen-dependent, tamoxifen-sensitive MCF7 cells." (PMID 29326587, 2017). "In our previous study, the pharmacological and siRNA-mediated blockade of HDAC2 or HDAC3 resulted in the down-regulation of the intermediate-conductance Ca2+-activated K+ channel KCa3.1 in human breast cancer YMB-1 cells." (PMID 27973439, 2016). "Presently SAR studies involving 5l and related analogs, with HDAC2 as drug target (for breast cancer) is ongoing in our lab." (PMID 27573798, 2016). "For example, VPA suppresses breast cancer cell migration by specifically targeting HDAC2 and down-regulating survivin." (PMID 23144972, 2012). "HDAC2 is associated with poor survival and relapse of cancer, HDAC3 promotes oncogenesis and is a good target for therapeutics, HDAC5 is known to increase the stemness of breast cancer cells, and HDAC7 protein is associated with reoccurrence of breast cancer." (PMID 40426890, 2025).